LMAN1 (lectin, mannose binding 1)
Description:
Mannose-specific lectin. May recognize sugar residues of glycoproteins, glycolipids, or glycosylphosphatidyl inositol anchors and may be involved in the sorting or recycling of proteins, lipids, or both. The LMAN1-MCFD2 complex forms a specific cargo receptor for the ER-to-Golgi transport of selected proteins.
Synonyms: ERGIC53; F5F8D; MR60; ERGIC-53; gp58; MCFD1; FMFD1
Tractability: Antibody: UniProt predicts a signal peptide or a membrane-spanning region. PROTAC: ubiquitination databases record sites on it; its protein half-life has been measured.
Gene: Protein-coding gene on chromosome 18 (59,327,823 to 59,359,265, reverse strand). Ensembl gene ENSG00000074695.
Subcellular location: Endoplasmic reticulum-Golgi intermediate compartment membrane; Golgi apparatus membrane; Endoplasmic reticulum membrane
Subcellular location (Human Protein Atlas): Vesicles; Endoplasmic reticulum
Pathways (Reactome):
Signal Transduction: RAC2 GTPase cycle; RAC3 GTPase cycle; RHOA GTPase cycle; RHOC GTPase cycle; RHOD GTPase cycle; RHOG GTPase cycle
Vesicle-mediated transport: COPII-mediated vesicle transport; Cargo concentration in the ER
Metabolism of proteins: Transport to the Golgi and subsequent modification
Gene Ontology:
Molecular function: metal ion binding; protein binding; D-mannose binding
Biological process: early endosome to Golgi transport; Golgi organization; negative regulation of establishment of protein localization to mitochondrion; blood coagulation; endoplasmic reticulum to Golgi vesicle-mediated transport; protein folding
Cellular component: cargo receptor complex; endoplasmic reticulum; endoplasmic reticulum-Golgi intermediate compartment; endoplasmic reticulum-Golgi intermediate compartment membrane; extracellular exosome; extracellular matrix; membrane; COPII-coated ER to Golgi transport vesicle; endoplasmic reticulum membrane; ER to Golgi transport vesicle membrane; Golgi membrane; endomembrane system; Golgi apparatus; sarcomere
Genetic constraint (gnomAD): Loss-of-function variants: 29 observed, 58.01 expected, observed/expected ratio (o/e) 0.5, 90% interval 0.37 to 0.68. The upper end of that interval is the gene's LOEUF score, 0.68, which puts it in group 2 of 6, group 1 being the genes least tolerant of losing a copy. Missense variants: 566 observed, 591.57 expected, observed/expected ratio (o/e) 0.96, 90% interval 0.89 to 1.03. Synonymous variants: 216 observed, 211.53 expected, observed/expected ratio (o/e) 1.02, 90% interval 0.91 to 1.14.
Gene-disease validity (ClinGen):
ClinGen rates the evidence that LMAN1 causes each of these diseases.
factor V and factor VIII, combined deficiency of, type 1 (autosomal recessive): Definitive.
Homologues: Orthologues: chimpanzee LMAN1 (99% identical), macaque LMAN1 (97% identical), pig LMAN1 (93% identical), rabbit LMAN1 (91% identical), dog LMAN1 (91% identical), rat Lman1 (89% identical), mouse Lman1 (89% identical), guinea pig LMAN1 (85% identical), tropical clawed frog lman1 (71% identical), zebrafish lman1 (66% identical), Drosophila melanogaster CG5510 (19% identical), Caenorhabditis elegans ile-2 (16% identical). Paralogues in human: LMAN1L (34% identical), LMAN2 (21% identical), LMAN2L (20% identical).
Diseases named in the same sentence as LMAN1 in open-access papers:
LMAN1 is named in the same sentence as 41 diseases in open-access papers, as found by Europe PMC text mining. Sharing a sentence is not in itself a finding about the gene and the disease. The quoted sentences say what the papers report.
bleeding disorder (3 papers, 2020 to 2024). "The identification of loss-of-function mutation in LMAN1 as the cause of the autosomal recessive human bleeding disorder combined factor V and factor VIII deficiency (F5F8D) identified these two proteins as putative cargoes for LMAN1." (PMID 36594468, 2023). "In humans, genetic deletion of either subunit of a cargo receptor complex, LMAN1/MCFD2, results in a rare bleeding disorder due to the impaired secretion of coagulation factors V and VIII, with a similar phenotype in Lman1-/-and MCFD2-/- mice." (PMID 31978056, 2020).
colorectal cancer (2 papers, 2012 to 2020). A primary or metastatic malignant neoplasm that affects the colon or rectum. "Another interesting example is mutation of the ER-to-Golgi trafficking protein LMAN1 in colorectal cancers, which causes reduced secretion of the LMAN1 client protein α-1-antitrypsin (A1AT; also known as SERPINA1), an angiogenesis inhibitor, thereby contributing to tumour blood supply and growth." (PMID 32433026, 2020). "Also, the frequency of mutations seen here is comparable to the previously reported frequency in MSI-positive colorectal cancer and emphasizes the importance of ACVR2A and TGF-β signaling in MSI-positive GC, while unraveling the oncogenic roles of RPL22 and LMAN1 requires further investigation." (PMID 23237666, 2012).
gastric cancer (2 papers, 2012 to 2015). A primary or metastatic malignant neoplasm involving the stomach. "In MSI-positive GCs, ACVR2A, RPL22, LMAN1, and STAU2 were observed to have recurrent single base thymine deletions in poly(T) regions and this was confirmed in a screen of an additional 94 gastric cancer/normal paired samples (9 MSI-positive)." (PMID 23237666, 2012).
airway hyperresponsiveness (1 paper, 2025). "Surprisingly, we discovered that loss of LMAN1 led to opposing effects on airway hyperresponsiveness (AHR), which were dependent on the sex of the mice." (PMID 40517435, 2025). "We showed that loss of LMAN1 influences airway hyperresponsiveness (AHR) in a sex-dependent manner in response to HDM." (PMID 40517435, 2025).
allergic asthma (1 paper, 2025). A asthma with a basis in a pathological type I hypersensitivity reaction. "In the current work, we investigate the in vivo relevance of LMAN1 in a murine model of HDM-induced allergic asthma." (PMID 40517435, 2025). "This work not only highlights the complexity of the loss of LMAN1 in vivo but also suggests that such sex-dependent responses should be taken into consideration when pursuing LMAN1 as a therapeutic target for treatment of allergic asthma." (PMID 40517435, 2025). "In this work, we investigated the role of LMAN1 in a physiologically relevant mouse model of allergic asthma and showed that LMAN1 regulates both AHR and the inflammatory response to HDM in a sex-dependent manner." (PMID 40517435, 2025). "While these findings suggested that LMAN1 could potentially be an effective therapeutic target, a better understanding of its role in allergic asthma was needed." (PMID 40517435, 2025). "In this follow-up work, we investigated the in vivo relevance of LMAN1 by subjecting LMAN1 knockout (KO) mice and wild type (WT) littermate controls to a model of HDM-induced allergic asthma." (PMID 40517435, 2025).
asthma (1 paper, 2025). "To investigate the role of LMAN1 in allergen-induced AHR, we subjected wild-type (WT) and LMAN1 knockout (KO) mice to a HDM asthma model." (PMID 40517435, 2025). "We further identified the features of HDM-induced asthma which may account for the gender-biased effects of LMAN1 on lung function." (PMID 40517435, 2025). "Uncovering the mechanisms of LMAN1 signaling and understanding its effects in different contexts may open possibilities for targeting this receptor with therapeutics that help address the unmet need in treatments for severe asthma." (PMID 40517435, 2025). "Given that RAGE is currently being explored as a therapeutic target for asthma, further studies will be needed to elucidate how this pathway could be regulated sex-dependently in response to HDM, and how it could be influenced by loss of LMAN1." (PMID 40517435, 2025).
bladder cancer (1 paper, 2018). "Furthermore, LINC00857 knockdown sensitized UM‐UC‐3 and T24 bladder cancer cells to cisplatin, via the negative regulation of the LMAN1 gene." (PMID 29856124, 2018). "We further evaluated the expression of DIAPH3, LMAN1, PPP2R5E, and UHMK1 in bladder cancer cell lines upon LINC00857 knockdown." (PMID 29856124, 2018).
breast carcinoma (1 paper, 2021). "Five proteins (LMAN1, AZI2, STAU2, MMP9 and PLOD1) from a systemic analysis of a variety of array data of breast cancer patients were subjected to immunofluorescence staining to evaluate the presence of fixed WBCs on 96-well plates from 363 healthy females and 358 female breast cancer patients." (PMID 33441653, 2021).
coagulation disorder (1 paper, 2023). "Combined deficiency of coagulation factors V and VIII (F5F8D) is an autosomal recessive coagulation disorder caused by mutations in LMAN1 or MCFD2." (PMID 37978530, 2023).
Congenital thrombocytopenia (1 paper, 2024). Thrombocytopenia with congenital onset. "The normal platelet volume observed in Lman1–/– mice is consistent with the generally normal platelet size in patients with congenital thrombocytopenia resulting from a defect in TPO/TPO receptor signaling." (PMID 39499573, 2024).
Dyskinesia (1 paper, 2021). A movement disorder which consists of effects including diminished voluntary movements and the presence of involuntary movements. "ADAM32 (Hoehn and Yahr), IRAK3 (dyskinesia), LMAN1 (UPDRS part 2), and RHD (dyskinesia) passed MR-Egger intercept, Cochran’s Q and I2 tests." (PMID 34930919, 2021).
emphysema (1 paper, 2022). "Mild decreases in AAT levels in LMAN1 and MCFD2 deficient male mice are insufficient to cause AATD symptoms such as COPD and emphysema." (PMID 35322856, 2022).
lung fibrosis (1 paper, 2025). "Mice lacking relaxin show enhanced lung fibrosis and AHR both at baseline and in response to allergen, suggesting that sex-dependent modulation of this pathway could possibly explain the effects of LMAN1 on AHR." (PMID 40517435, 2025).
microphthalmia (1 paper, 2015). Congenital or developmental anomaly in which the eyeballs are abnormally small. "However, retinal progenitor cell proliferation and retinal lamination are normal in Lman1-deficient mice, suggesting that downregulation of Lman1 in Brg1-deficient retinae is not the major cause of the microphthalmia and retinal lamination defects in our analyses." (PMID 26628093, 2015).
retinal disease (1 paper, 2012). "Based on putative function and/or involvement in retinal disease, we selected 16 genes – Bach2, Cdr2, Dusp12, Esrrb, Gpsm2, Haus1, Kdm5b, Lman1, Lrp11, Lrrc2, Ncoa2, Plekha2, Ppargc1b, Trim36, Wisp1 and Zdhhc14." (PMID 22511886, 2012).
Thrombocytopenia (1 paper, 2024). A reduction in the number of circulating thrombocytes. "In this study, we showed that LMAN1-deficient mice (with complete germline LMAN1 deficiency) exhibited mild thrombocytopenia, whereas the platelet count was entirely normal in mice with approximately 7% Lman1 expression." (PMID 39499573, 2024). "Consistent with the earlier data, analysis of singly deficient mice verified the previously noted mild thrombocytopenia in Lman1–/– mice (with average platelet count ~70% of WT) with normal platelet counts in MCFD2-deficient mice." (PMID 39499573, 2024). "To determine if reduced Lman1 expression to about 7% of normal results in thrombocytopenia, we analyzed complete blood counts in blood samples obtained from the latter mice." (PMID 39499573, 2024). "Collectively, these results, taken together with LMAN1’s known function as an ER cargo receptor, strongly suggest that the thrombocytopenia observed in Lman1–/– mice is due to impaired secretion of TPO from hepatocytes." (PMID 39499573, 2024). "Taken together, these results suggest that the thrombocytopenia observed in Lman1–/– mice results from a potentially novel LMAN1-specific (but MCFD2 independent) function, affecting MK/platelet differentiation or survival." (PMID 39499573, 2024). "Since TPO is a major hepatocyte-derived regulator of platelet synthesis, we reasoned that TPO production, stability, or secretion could be impaired in Lman1–/– mice, resulting in thrombocytopenia." (PMID 39499573, 2024). "LMAN1/MCFD2 double deficient mice exhibited thrombocytopenia, with platelet counts indistinguishable from Lman1–/– mice." (PMID 39499573, 2024). "We now report that LMAN1-deficient, but not MCFD2-deficient mice, exhibit thrombocytopenia and that mice with combined deficiency of LMAN1 and MCFD2 exhibit thrombocytopenia indistinguishable from that in LMAN1-deficient mice." (PMID 39499573, 2024). "Therefore, we hypothesize that the relatively subtle degree of thrombocytopenia detected in our Lman1-null mice would likely be missed among the diverse population of human patients with F5F8D, particularly given that a 20%–30% reduction in platelet count is still well within the normal range." (PMID 39499573, 2024). "Mice with Lman1 deletion restricted to hepatocytes exhibited significant thrombocytopenia relative to WT controls (P < 0.012), with platelet counts indistinguishable from those in ubiquitous Lman1-null mice." (PMID 39499573, 2024). "We next showed that hepatocyte-specific but not hematopoietic Lman1 deletion results in thrombocytopenia, with plasma TPO level reduced in LMAN1-deficient mice, despite normal Tpo mRNA levels in LMAN1-deficient livers." (PMID 39499573, 2024). "Tissue-specific deletion of Lman1 results in thrombocytopenia in mice with hepatocyte-specific Lman1 deletion but not in mice with deletion of Lman1 in hematopoietic cells." (PMID 39499573, 2024). "Lman1 deletion in hepatocytes, but not hematopoietic cells, results in thrombocytopenia." (PMID 39499573, 2024). "Thus, the thrombocytopenia observed in Lman1–/– mice is not due to a defect intrinsic to MKs, platelets, or a hematopoietic cell." (PMID 39499573, 2024). "In contrast with mice with hepatocyte-specific Lman1 deletion, mice with deletion of Surf4 in hepatocytes did not exhibit thrombocytopenia, suggesting that SURF4, unlike LMAN1, does not play a role in the secretion of TPO under steady-state conditions." (PMID 39499573, 2024).
vasculitis (1 paper, 2018). "Indeed, several miRNAs targeted DEGs associated with blood coagulation (i.e., THBS1, F5, and LMAN1), a process whose alteration is typically associated with BD vasculitis." (PMID 29854829, 2018).
cancer (4 papers, 2021 to 2025). A tumor composed of atypical neoplastic, often pleomorphic cells that invade other tissues. "Other pathways highlighted by our analysis include ABC transporters, Wnt signaling, and miRNAs in cancer, all of which warrant further investigation in relation to LMAN1." (PMID 40517435, 2025). "LMAN1 cMS mutations have been previously detected in hereditary MSI adenomas and suggested to play a role in early MSI-driven carcinogenesis, which could explain their high frequency in incident cancers." (PMID 34206061, 2021).
inflammation (2 papers, 2021 to 2025). Aberrant reaction of the microcirculation characterized by movement of fluid and leukocytes from the blood into extravascular tissues. "LMAN1 has also been associated with coagulation, and both TNFAIP2 and HLA-DQB1 are associated with vascular inflammation." (PMID 33961016, 2021).
hematological disease (1 paper, 2022). "In addition, genes associated with hematological disease (e.g., PDE7A, LMAN1, F13A1, OLR1) and mitochondrial biogenesis and redox (e.g., NOS3, ALDH5A1, PRXL2A, SLC25A13, CPT2) were also significantly altered in BPD patients." (PMID 35484630, 2022).
LMAN1 also shares sentences with these, for which no sentence is quoted: infection (9 papers); tumor (3); glioma (2); Autoimmunity (1); cholestasis (1); diabetes (1); epilepsy (1); gastric tumors (1); Immunodeficiency (1); insulinoma (1); Intellectual disability (1); mastitis (1); medulloblastoma (1); melanoma (1); Obesity (1); ovarian carcinoma (1); retina degeneration (1); synovitis (1); thrombosis (1); virus infection (1); Von Willebrand disease (1).